CDK4 (cyclin dependent kinase 4)
Diseases named in the same sentence as CDK4 in open-access papers (continued):
Sharing a sentence is not in itself a finding about the gene and the disease.
pulmonary hypertension (3 papers, 2021 to 2024). Increased pressure within the pulmonary circulation due to lung or heart disorder. "Pulmonary arteries and human pulmonary arterial smooth muscle cells from patients with pulmonary arterial hypertension display a decreased level of CDK4 disulfide, consistent with CDK4 being hyperactive in human pulmonary arterial hypertension." (PMID 37955182, 2023). "It was recently found that the oxidation of CDK4 triggers the formation of a reversible intermolecular disulfide bond between Cys135 of CDK4 and Cys7/8 of cyclin D, which inhibits cyclin D-CDK4 activity, consequently reducing cell proliferation in a mouse model of pulmonary hypertension." (PMID 38972297, 2024).
seminoma (3 papers, 2020 to 2023). A radiosensitive malignant germ cell tumor found in the testis (especially undescended), and extragonadal sites (anterior mediastinum and pineal gland). "Our data revealed that YAP1/CDK6/CDK4/cyclinD1/RB could be a potential therapeutic axis in TGCTs and sequential regimens of metformin and cisplatin could be a useful therapy for human seminomas and non-seminomas." (PMID 35264157, 2022). "Subsequently, a gene expression analysis via RT-qPCR was performed for the non-seminoma marker SOX2; the cytokine IL6, which is moderately produced also through tumor cells; and the proliferation and cell cycle genes KI67 and CDK4." (PMID 37174085, 2023). "CDK4/CDK4 was highly expressed in GCT tissues (GCNIS, seminomas, ECs, teratomas) and cell lines (TCam-2, seminoma; 2102EP, NCCIT, both EC; JAR, choriocarcinomas)." (PMID 32418994, 2020). "Among them, we found the cell cycle- and CDK4/6-associated genes CCND2 (seminomas 9.8%, non-seminomas 16.8%), CDKN1B (P27; seminomas 15.3%, non-seminomas 16.4%) and MDM2 (seminomas 4%, non-seminomas 3.6%) commonly amplified in seminomas and non-seminomas." (PMID 32418994, 2020). "We also confirmed CDK4 expression on protein level by immunohistochemistry of formalin-fixed-paraffin-embedded GCT tissues and found mainly cytoplasmatic, but also nuclear staining in seminomas (n = 8), ECs (n = 7), yolk-sac tumours (n = 4) and teratomas (n = 3)." (PMID 32418994, 2020).
steatosis (3 papers, 2020 to 2024). Increased lipid within the cytoplasm of cells. "Furthermore, the aging-induced upregulation of the cyclin-dependent kinase-4 (cdk4) phosphorylates CCAAT enhancer-binding protein (C/EBP α) and formation of C/EBPa-p300 complexes causing steatosis, and CDK-4 inhibition, was shown to lower steatosis." (PMID 34836382, 2021). "The mutant C/EBPα-S193D mice have accelerated cdk4-dependent pathway and have developed steatosis at early stages." (PMID 37967813, 2024). "CDK4 is a critical regulatory enzyme and patients with steatosis and NASH have increased levels of CDK4." (PMID 33334026, 2020). "C/EBPα is the main target of CDK4 which mediates phosphorylation of C/EBPα at Ser193 and stimulates C/EBPα/histone acetyltransferase p300 (p300) complex formation and increases steatosis in mice." (PMID 33334026, 2020).
Stomach Cancer (3 papers, 2019 to 2023). "Notably, CDK4 and CDK6 were significantly upregulated in gastric tumors than adjacent normal tissues and were dysregulated among GC patients." (PMID 36755269, 2023).
stomatitis (3 papers, 2020 to 2025). Inflammation of the oral mucosa due to local or systemic factors. "Taken together, these findings are consistent with a potential mechanistic gradient, where inhibition of PI3K or mTOR more strongly predisposes to stomatitis than targeting at the level of CDK4/6 or AKT." (PMID 41155694, 2025). "Our data may suggest that drugs targeting the PI3K/AKT/mTOR pathway, particularly PI3K and mTOR inhibitors, are associated with a higher risk of stomatitis than downstream targets such as CDK4/6." (PMID 41155694, 2025). "Stomatitis is described in pivotal studies (palbociclib—PALOMA; ribociclib—MONALEESA; and abemaciclib—MONARCH) as an adverse effect associated with the use of the three CDK4/6 inhibitors." (PMID 38248101, 2024). "Oral mucositis, specifically stomatitis characterized by aphthous ulcer, occurs in very few patients treated with cyclin-dependent kinase 4/6 inhibitors (CDK4/6), used as first- or second-line treatment for hormone positive/HER2 negative metastatic breast cancer." (PMID 33028357, 2020). "Importantly, we also observed a higher disproportional reporting rate associated with alpelisib compared to palbociclib, suggesting that PI3K inhibition may more directly contribute to stomatitis pathophysiology than CDK4/6 inhibition." (PMID 41155694, 2025).
T-cell leukemia (3 papers, 2005 to 2022). A malignant disease of the T-lymphocytes in the bone marrow, thymus, and/or blood. "Pimozide, an inhibitor of USP1, results in the arrest of adult T-cell leukemia cells in the G1 phase, leading to the accumulation of p21 and p27 and reduction in the protein levels of cyclin D2, cyclin E, CDK2, CDK4, and CDK6." (PMID 36357365, 2022). "It is found in active CDK holoenzyme complexes from adult T-cell leukemia-derived cultures and stimulates the G1- to-S phase transition by activating the cyclin-dependent kinase (CDK) CDK4." (PMID 16164752, 2005).
Thromboembolism (3 papers, 2024). The formation of a blood clot inside a blood vessel that subsequently travels through the blood stream from the site where it formed to another location in the body, generally leading to vascular occlusion at the distant site. "The thromboembolism rates in real-world patients treated with CDK4/6 inhibitors are higher than those reported in clinical trials, and the application of prophylactic anticoagulation in this patient population may be questionable." (PMID 38327739, 2024).
thrombosis (3 papers, 2021 to 2025). "Increased VTE reporting emerged for CDK4/6 inhibitors in the exploratory analyses (n = 659; ROR = 1.51; 95% CI = 1.39–1.63), with consistent disproportionality in the consolidated analyses (e.g., deep vein thrombosis with abemaciclib: 17; 1.98; 1.22–3.19)." (PMID 33917020, 2021).
vitiligo (3 papers, 2023 to 2025). Generalized well circumscribed patches of leukoderma that are generally distributed over symmetric body locations and is due to autoimmune destruction of melanocytes. "Although its precise etiology remains incompletely elucidated, emerging evidence confirms an association between CDK4/6 inhibitor therapy and vitiligo development." (PMID 41438984, 2025). "Therefore, vitiligo-like skin lesions have been infrequently reported in the literature, although they are recognized in clinical practice as adverse events associated with the use of CDK4/6 inhibitors." (PMID 40422590, 2025). "The median patient age was 71.5 years, with vitiligo onset occurring between 2 to 11 months post-CDK4/6 inhibitor treatment." (PMID 41438984, 2025). "Some data on skin toxicities, including vitiligo-like lesions by CDK4/6 inhibitors, have recently been reported in the literature, but for the first time, we highlight a possible correlation with improved survival outcomes of patients." (PMID 36969030, 2023). "Based on this evidence, we hypothesize that while activating antitumor immune responses, CDK4/6 inhibitors may disrupt autoimmune tolerance toward melanocytes, consequently triggering vitiligo development." (PMID 41438984, 2025). "Cases of vitiligo in patients after using CDK4/6 inhibitors." (PMID 41438984, 2025).
Wilms tumor (3 papers, 2015 to 2024). An embryonal neoplasm characterized by the presence of epithelial, mesenchymal, and blastema components. "Knock-down of PIK3R3 confirmed that ZSTK474 downregulated PIK3R3, reducing Akt phosphorylation, cyclin D and CDK4 levels and elevating P21 expression in nephroblastoma cells." (PMID 39466763, 2024). "Faussillon M have found CDK4 are frequent overexpression and had a specific correlation between relapse and CDK4 overexpression in Wilms' tumor." (PMID 26036633, 2015). "Though CNVs in genes involved with cell cycle regulation were evident, such as CDK4 and CCND2 copy number gains (three copies of each gene) compared to primary Wilms tumor samples [HT98 and HT139]." (PMID 36612255, 2022).
anaplastic thyroid cancer (2 papers, 2022 to 2024). "The effects of CDK4/6 inhibitors in patients with anaplastic thyroid cancer will have to await the outcome of clinical trials." (PMID 35406382, 2022).
asthenia (2 papers, 2024 to 2025). Clinical sign or symptom manifested as debility, or lack or loss of strength and energy. "Finally, regardless of the CDK4/6i, asthenia is reported in approximately 40% of the FDA pooled analysis patients, increasing to over 50% in ≥70 years old." (PMID 38791919, 2024).
bladder tumors (2 papers, 2005 to 2018). "Conversely, limiting CDK4/6 dependent RB phosphorylation by palbociclib was additive with selinexor in reducing bladder tumor cell viability, confirming that RB activity has a role in the response to XPO1 inhibition." (PMID 30349650, 2018). "While mutated or deleted RB cannot be replaced, preclinical studies utilizing CDK4/6 inhibitors have shown that these compounds have efficacy in retarding growth of certain bladder tumors in an RB dependent manner." (PMID 30349650, 2018). "In agreement with the gene expression profile, we found an increased protein expression of CDK4 in cancer cells from bladder tumours." (PMID 16265353, 2005).
cardiac hypertrophy (2 papers, 2020 to 2025). "To further investigate the effect of TP on the protein expression of cell cycle regulators in NRVMs, we examined the expression of several cell cycle-specific proteins, cyclin D1, CDK4 and 6, and P21, on cardiac hypertrophy progression." (PMID 33013405, 2020).
Cervical tumors (2 papers, 2016 to 2020). "It is of note that, in HPV-associated cervical tumors, D-type cyclins and CDK4/6 activity inhibition by p16INK4a promotes tumor cell survival." (PMID 32224897, 2020). "Cervical tumors are therefore likely to be sensitive to CDK4/6 inhibitors." (PMID 26701206, 2016).
corticotroph adenoma (2 papers, 2018 to 2024). "Martins and colleagues conducted a study to investigate the USP8 variant and its contribution to gene expression of cell cycle regulators including P27/CDKN1B, CCNE1, CCND1, CDK2, CDK4, and CDK6 in 32 corticotroph adenoma." (PMID 38862897, 2024).
cyst (2 papers, 2022 to 2025). A sac-like closed membranous structure that may be empty or contain fluid or amorphous material. "The experimental HOVs-cyst-1 cells were first established from serous cystadenoma epithelial cells of the ovary without any existing carcinomas and then immortalized by overexpression of cyclin D1, CDK4, and hTERT." (PMID 35326657, 2022). "By modulating the Cyclin D1/CDK4/Rb axis and p19 regulation, ANKHD1 inhibition could potentially slow cyst growth and disease progression." (PMID 40457431, 2025).
dwarfism (2 papers, 2023 to 2025). "Here we report the identification and functional characterization of biallelic loss-of-function (LOF) mutations in CDK4 in individuals with microcephalic dwarfism." (PMID 40210435, 2025). "Therefore, although strictly not fulfilling the criteria for “primary,” where microcephaly is evident at birth, the CDK4 phenotype otherwise parallels primary microcephaly and overlaps with microcephalic dwarfism." (PMID 40210435, 2025).
endometrioid endometrial carcinoma (2 papers, 2019 to 2023). "Conversely, the Rbsig signature showed higher score in uterine CCC (p = 0.082), suggesting lesser vulnerability to CDK4/6 inhibitors than in endometrioid endometrial carcinoma." (PMID 37353806, 2023). "CDK4 promotes progression of the cell cycle and increased expression is observed in 34–77% of endometrioid endometrial carcinoma (EEC)." (PMID 31053132, 2019).
esophageal adenocarcinoma (2 papers, 2017 to 2025). A malignant tumor with glandular differentiation arising predominantly from Barrett mucosa in the lower third of the esophagus. "Treatment with abemaciclib of rats bearing esophageal adenocarcinoma xenografts, established from three different cell lines, resulted in tumor volume reduction and down-regulation of cyclin D, CDK4, CDK6 and E2F1, compared with rats treated with placebo." (PMID 40699853, 2025). "Knockdown of CDK6 or CDK4 with small interfering RNA or pharmacologic inhibition with palbociclib led to proliferation suppression and inhibition of anchorage-independent survival in esophageal adenocarcinoma cells." (PMID 40699853, 2025).
fibrous dysplasia (2 papers, 2020 to 2022). A genetic, non-inheritable disorder caused by osteoblastic differentiation defects that result in the replacement of bone marrow and trabecular bone by fibrous stroma and immature bone. "With regard to histopathologically differentiating OSJ from fibrous dysplasia and other benign fibrous and fibro-osseous lesions, immunohistochemical expression of murine double-minute type 2 MDM2) and cyclin-dependent kinase 4 (CDK4) may be helpful." (PMID 33125360, 2020).
gliosarcoma (2 papers, 2020 to 2021). A rare histological variant of glioblastoma (WHO grade IV) characterized by a biphasic tissue pattern with alternating areas displaying glial and mesenchymal differentiation (WHO). "Based on the detected CDKN2A/B deletion, we further tested the potential of the CDK4/6 inhibitor abemaciclib, which showed strong efficacy against both gliosarcoma cell models and entrectinib distinctly synergized with 5 μM abemaciclib in vitro." (PMID 33353026, 2020).
Glucose intolerance (2 papers, 2023 to 2024). Glucose intolerance (GI) can be defined as dysglycemia that comprises both prediabetes and diabetes. "Since homozygous Cdk4-R24C alleles rescued glucose intolerance in male mice by correcting insulin deficiency, we predicted that β cell function, mass, or both were restored in Irs2–/–;Cdk4-R24C/R24C mice." (PMID 37712417, 2023). "The cyclin‐dependent kinase 4 (CDK4) nucleotide substitution confers protection to CDK4 from inhibition by the INK family of cell cycle inhibitors, thereby ameliorating glucose intolerance in IRS2‐deficient mice." (PMID 39355507, 2024). "Here, we report that replacing both alleles of Cdk4 with Cdk4-R24C rescued glucose intolerance in IRS2-null mice without improving insulin sensitivity." (PMID 37712417, 2023).
Hepatitis (2 papers, 2023 to 2024). Inflammation of the liver. "The median time from the introduction of CDK4/6 inhibitors to hepatitis occurrence was 73 days (IQR 41.5–107.75)." (PMID 38961854, 2024). "The utility of corticosteroids in managing drug-induced hepatitis and the feasibility of resuming CDK4/6 inhibitor therapy post-recovery are notable practical outcomes." (PMID 38961854, 2024). "In this study, we report on 22 cases of hepatitis induced by CDK4/6 inhibitors (ribociclib, n = 19 and abemaciclib, n = 3)." (PMID 38961854, 2024). "•The study reports on 22 cases of CDK4/6 inhibitor-induced hepatitis, providing significant insights into its clinical and biochemical features." (PMID 38961854, 2024). "When resuming treatment, a different CDK4/6 inhibitor was used from the one involved in hepatitis." (PMID 38961854, 2024). "In five patients, anti-cancer therapy was resumed, including three patients treated with a CDK4/6 inhibitor (abemaciclib n = 2 and palbociclib n = 1), with follow-up between 72 and 212 days without hepatitis recurrence." (PMID 38961854, 2024). "As already reported in the literature, there seems to be no class effect in anti-CDK4/6 rechallenge after hepatitis." (PMID 38961854, 2024). "Furthermore, in patients with a history of anti-CDK4/6-induced liver injury, exposure to another CDK4/6 inhibitor does not seem to be associated with hepatitis relapse, suggesting the absence of cross-direct hepatotoxicity or the development of an adaptation to this drug family." (PMID 38961854, 2024).
Hyperinsulinemia (2 papers, 2023 to 2025). An increased concentration of insulin in the blood. "Plasma insulin measurements confirmed hyperinsulinemia in Irs2–/–;Cdk4-R24C/R24C males, suggesting rescue of insulin secretory capacity in the context of at least some residual insulin resistance." (PMID 37712417, 2023). "Fat mass was increased in Irs2–/–; Cdk4-R24C mice, although this could have been secondary to hyperinsulinemia." (PMID 37712417, 2023).
insomnia (2 papers, 2024 to 2025). A sleep disorder characterized by difficulty in falling asleep and/or remaining asleep. "Adverse events such as insomnia, anxiety, fatigue, and bone pain should also be considered for CDK4/6 inhibitors because they negatively affect patients’ QoL." (PMID 40277749, 2025). "Among these PAEs, insomnia, stress, eating disorder, depressed mood, and sleep disorder were very common, each accounting for over 10% of CDK4/6i reports." (PMID 39009505, 2024). "In the findings from a multi‐country survey, PAEs including low sexual interest, anxiety, and insomnia occurred in 50%, 34%, and 14% of patients on CDK4/6i treatment, respectively, severely affecting their quality of life." (PMID 39009505, 2024).
ischemia (2 papers, 2021). A hypoperfusion of the BLOOD through an organ or tissue caused by a PATHOLOGIC CONSTRICTION or obstruction of its BLOOD VESSELS, or an absence of BLOOD CIRCULATION. "In this study, we examined changes in cyclin D1, cdk4, and related molecules in cells or neurons located in Cornu Ammonis 1 (CA1) of gerbil hippocampus after transient ischemia for 5 min (ischemia and reperfusion) and investigated the effects of IPC on these molecules after ischemia." (PMID 34439951, 2021).
lipoblastoma (2 papers, 2024 to 2025). A lipoma usually occurring in the extremities of young children (usually boys). "Lipoblastomas are the most common adipocytic tumors in children, but if a tumor is located in the deep tissue or imaging findings are not typical, the possibility of ALT should be considered and immunohistochemistry for MDM2 and CDK4 should be added." (PMID 39109289, 2024).
liver fibrosis (2 papers, 2017 to 2024). "However, the role of CDK4 in liver fibrosis remains largely unknown." (PMID 28095789, 2017).
lung fibrosis (2 papers, 2021 to 2024). "The mechanisms of ILD are unknown, and someone may even consider ILD with CDK4/6 inhibitors a paradoxical event since the anti-proliferative mode of action of these agents can be theoretically useful in counteracting lung fibrosis." (PMID 33150548, 2021).
monocytic leukemia (2 papers, 2010 to 2025). "We found that celastrol could arrest human monocytic leukemia cells U937 at G0/G1 phase, this arrest accompanied by down-regulation of Cyclin D1, Cdk4, Cdk6, and Cdk2." (PMID 20398364, 2010).
muscular dystrophies (2 papers, 2011 to 2020). "Here, we used CDK4/hTERT expression in primary MuSCs and we derived MuSC clones from a series of clinically and genetically characterized patients, including eight DMD patients with various mutations, four congenital muscular dystrophies and three age-matched control muscles." (PMID 32722643, 2020). "Primary cultures from distinct muscular dystrophies (DMD, FSHD, OPMD, CMD and LGMD2B) were co-transduced with two retroviral vectors expressing hTERT and CDK-4 cDNA." (PMID 22040608, 2011). "In the present study, we used CDK4/TERT expression in primary MuSCs to derive novel MuSC clones from a series of DMD, congenital muscular dystrophies (that can serve as non-DMD myopathic samples) and age-matched control muscles." (PMID 32722643, 2020).